IL10 (interleukin 10)
Diseases named in the same sentence as IL10 in open-access papers (continued):
Sharing a sentence is not in itself a finding about the gene and the disease.
Obesity (continued). "In obesity condition, it is observed a disbalance on this secretion, where a greater release of pro-inflammatory cytokines (Leptin, IL-6, TNF-α among others) is seen in detriment to anti-inflammatory cytokines (Adiponectin and IL-10)." (PMID 31749764, 2019). "Circulating IL10 levels have been shown to be either negatively, positively or not correlated with obesity and fat mass content in humans." (PMID 30158466, 2018). "This anti-obesity effects of lack of IL10 are related to a heightened EE despite increases in LFD food intake were concomitantly found." (PMID 30158466, 2018). "Taking together, these results and the key immunomodulatory role of IL10 suggest that the IL10/IL10RA might act as a brake to limit fat burning and preserve fuel supplies in conditions of acute energy demands as infectious states but also in obesity and aging." (PMID 30158466, 2018). "These include obesity-related differences in tumor necrosis factor (TNF-α), interleukin-10 (IL-10), leptin, sympathetic nervous system responses, renin-angiotensin responses, the detoxification of lipopolysaccharides, and circulating atrial natriuretic peptides." (PMID 29216243, 2017). "Therefore, the potential mechanisms about the effect of exercise training in diseases condition (e.g., Obesity, diabetes type 2, sedentary, and others), which modulates the production of TNF-α by increasing IL-10." (PMID 29163201, 2017). "We report that, in obesity and CRC conditions, adipocyte microenvironment delivers immunosuppressive signals to differentiating DC, as assessed by their enhanced expression of inhibitory molecules and the reduced IL-12/IL-10 ratio." (PMID 27494857, 2016). "In this study, serum levels of the anti-inflammatory cytokine IL-10 showed a 15% reduction related to obesity itself (Controls versus MO) and a 35% decrease associated with OSA regardless of obesity (MO versus MO+OSA)." (PMID 25944984, 2015). "Irisin could contribute to the modulation of obesity-induced inflammatory/anti-inflammatory balance by increasing CD206 and interleukin 10 and decreasing tumour necrosis factor alpha and leptin." (PMID 25530809, 2014). "Collectively, these findings suggest that obesity-related hyperleptinemia is accompanied by a low-grade inflammatory profile, characterized by increased circulating levels of TNF-α and IL-12, and reduced concentrations of IL-10." (PMID 23986664, 2013). "The obesity-related adipose gene expression pattern was dramatically altered by the HF-FO diet, whereby expression of MCP-1, IL-6 and IFNγ mRNA levels were reduced and IL-10 mRNA expression was elevated, compared to HF." (PMID 23166761, 2012). "In addition, inflammatory cytokines associated with obesity-related immune responses, including TNF-α, IL-6, and IL-10, were not measured, limiting our understanding of the immunometabolic effects of LA-1." (PMID 40732971, 2025). "Laurate-bioconjugated fructans could be useful to counteract the adverse effects of a high-fat diet on the characteristics of MetS such as obesity, insulin resistance, high blood pressure, and hypertriglyceridemia, probably by decreasing food intake and modulating CRP and IL-10." (PMID 39204141, 2024). "In addition, the volunteers with obesity showed higher ratios between IL-1β and IL-10 (A, p < 0.0001), IP-10 and IL-10 (D, p < 0.05), TNF-α and IL-10 (E, p < 0.0001), IL-12p70 and IL-10 (F, p < 0.01), IFN-γ and IL-10 (G, p < 0.05), and GM-CSF and IL-10 (H, p < 0.0001) than the NW group." (PMID 39125408, 2024). "Similarly, in pregnant mice with obesity, there are increased levels of inflammatory markers, including TNF-α, IL-6, interleukin-1β (IL-1β), nuclear factor kappa-light-chain-enhancer of activated B cells (NFκB) and interleukin-10 (IL-10) in the placenta." (PMID 38671859, 2024).
Obesity (continued). "Inflammation of the adipose tissue is mediated by inflammatory cytokines, such as IL1-1β, IL-6, IL-8, IL-10, IL-12, and Tumor Necrosis Factor (TNF-α), as well as chemokines including MCP-1, which are produced by M1 macrophages in the adipose tissue of individuals with obesity." (PMID 38396489, 2024). "Moreover, significant changes in anti-inflammatory IL-10 detected in the placebo group suggest an attempt to restore homeostasis to counterbalance obesity-related inflammation, while no changes were detected in the cherry group." (PMID 36771387, 2023). "Additionally, in our study, we demonstrated the predictive value of the anti-inflammatory cytokine IL-10 for obesity (0.35 pg/mL), but not IR." (PMID 37373485, 2023). "We did not detect any effect of obesity or diet on liver IL-10 or IL-1β expression." (PMID 38075211, 2023). "The organism’s self-protection mechanism towards the periodontium via promoting IL-10 and inhibiting the expression of ROS and other pro-inflammatory markers mediated by adiponectin was suppressed in periodontitis rats with or without obesity in our study." (PMID 38069063, 2023). "The combination of obesity-related monocyte dysfunction and the suppressing effect of CRP on IL-10 secretion may explain the noted lack of association between GCF CRP and IL-10 in our results." (PMID 38138192, 2023). "Furthermore, numbers of IL-10-secreting macrophages are increased in WAT of women with obesity and T2D, but not in men." (PMID 36313784, 2022). "Interestingly, obesity‐related leptin concentration significantly increased the ability of purified CD4+ T cells from lean AA patients to produce IL‐5, IL‐13, IL‐17 and IL‐6, but diminished IL‐10 release." (PMID 35734271, 2022). "Moreover, the levels of IL-10 (P < 0.001), IL-4 (P < 0.001), and TNF-α (P < 0.001) in the sarcopenia group were higher than those in the non-sarcopenia group after adjusting for sex, age, hypertension, blood lipid concentration, and obesity." (PMID 36160136, 2022). "However, women with obesity and T2D had significantly higher circulating IL-10 compared to non-obese women with T2D (p=0.022)." (PMID 36313784, 2022). "However, at present we do not know the molecular mechanism of this upregulation and which factor increasing IL-10 production is absent in men with obesity and T2D." (PMID 36313784, 2022). "Therefore, ATM-derived IL-10 may be a promising indicator to monitor HGP homeostasis during fasting-feeding cycle and a potential therapeutic target for obesity-induced metabolic dysfunction." (PMID 36091076, 2022). "Other immune molecules, including INF-γ, IL-7, IL-10 and α-MSH/IgG, may have negative associations with obesity-related eating behaviors." (PMID 35911732, 2022). "According to the model we propose, the probability of progression to severe disease in hypertensive patients with obesity and diabetes is 0.1% in the absence of increased IL-10 and IL-12 (p70) levels, but 81.5% with levels of these two cytokines exceeding the 90% sensitivity thresholds." (PMID 34386533, 2021). "Moreover, the studies have shown that a decreased concentration of adiponectin and interleukin 10 and an increased concentration of leptin, resistin, interleukin 6, and MCP-1 could be a potential marker of obesity and its accompanying disorders." (PMID 34769133, 2021). "In patients with obesity, overproduction of cytokines evokes a preexisting chronic inflammation, since adipocytes secretion of pro-inflammatory molecules (e.g. MCP-1, IL-6, IL-18, TNF-α, IL-1β) together with a decrease of anti-inflammatory cytokines (e.g. IL-10) has been reported." (PMID 34038475, 2021). "However, when Treg-specific IL-10 was knocked down, the expression of uncoupled protein 1 (UCP1) and other thermogenic genes in adipocytes in white AT was increased, protecting mice from insulin resistance and diet-induced obesity." (PMID 34515616, 2021).
Obesity (continued). "Lower IL-10 production capacity has been demonstrated in obesity, implicating that the lack of IL-10 may, at least in part, contribute to the prevalent pro-inflammatory profile expressed in obesity." (PMID 31450770, 2019). "Although WAT simultaneously increases the release of anti-inflammatory cytokines, including IL-4, IL-10, and IL-2 to counteract the unfavorable effects of inflammation, WAT immunity eventually shifts toward an inflammatory state, leading to prolonged inflammation in obesity." (PMID 29951059, 2018). "Moreover, IL-10 expression was not reduced in obesity with normal blood triglycerides adult cohort, which is similar to our observation." (PMID 29895283, 2018). "We also provided evidence that, in obesity and CRC conditions, adipocyte microenvironment delivers immunosuppressive signals to differentiating dendritic cells (DC), as assessed by their enhanced expression of inhibitory molecules and reduced IL-12/IL-10 ratio." (PMID 30455701, 2018). "Moreover, IL-10 treatment inhibited these alterations in the pancreas in both SPX wild-type and IL-10KO mice, thus supporting the hypothesis that obesity-induced reductions in IL-10 derived from the spleen may result in pancreatic damage." (PMID 23285260, 2012). "Since IL-10 and TNF-α are expressed and released mainly from the stromal vascular fraction of the adipose tissue, these findings provide further evidence for altered inflammatory activity of immune cells in the epididymal fat depot of mice with long-standing obesity." (PMID 22051061, 2011). "Inflammatory adipokines [IL-6, IL-10, ACE, TGFβ1, TNFα, IL-1β, PAI-1, and IL-8] plus one anti-inflammatory [IL-10] adipokine were identified whose circulating levels as well as in vitro release by fat are enhanced in obesity and are primarily released by the nonfat cells of human adipose tissue." (PMID 20508843, 2010). "We show that the CR increased the expression levels of anti-inflammatory genes Il-10 and Adrbk1 and energy homeostasis-related genes such as Ptgds, Lpin2, Angptl6, Kcnj11, and Dusp9 but were not affected by obesity in HF mice." (PMID 20307313, 2010). "At the family level, Lachnospiraceae, Erysipelotrichaceae, and Bacteroidaceae, which were enriched in the obesity-related groups, either with or without Pso, displayed positive correlations with all the investigated proinflammatory cytokines and chemokines, except IL-10 and PF4." (PMID 40869018, 2025). "However, we also observed an increase in IL-10, a potent anti-inflammatory cytokine, in the liver of the groups treated with liposomes, which indicates an anti-inflammatory action of this extract even in the absence of obesity." (PMID 39452080, 2024). "Moreover, HIIT-induced IL-10 overexpression may suppress IL-β, IL-6, and TNF-α in mononuclear cells challenged with lipopolysaccharide and the transcription of IL-8 in polymorphonuclear leukocytes in individuals with obesity." (PMID 37608837, 2023). "Additionally, immune molecules, including interferon gamma (INF-γ), interleukin (IL)-7, IL-10, and α-melanocyte-stimulating hormone-reactive immunoglobulin G (α-MSH/IgG) immune complex, may have negative associations with obesity-related eating behaviors." (PMID 35911732, 2022). "This unique finding suggests the IL-6/IL-10 cytokine axis observed only in females may account for their lower weight gain compared to males during the period of DIO, and this strongly suggests sex as an important biological variable to be considered in obesity research." (PMID 34439950, 2021). "Similarly, other studies have not supported an anti-obesity role for IL-10." (PMID 34248663, 2021). "Therefore, we selected IL-10 expression-inducing Bifidobacterium adolescentis HP1, Lactobacillus mucosae HP2, and Weissella cibaria HP3 from a human fecal bacterial strain collection and examined their effects on HFD-induced obesity and liver steatosis in mice." (PMID 31986244, 2020).
Obesity (continued). "However, besides the CCR2 level, DARC+Ly6Clo ATMs express a higher level of IL-10, IDO, and TGF-β mRNA than those of DARC- cells, indicating that the DARC+Ly6Clo cells essentially function to revert the inflammatory status in diet-induced obesity to an anti-inflammatory status." (PMID 31817755, 2019). "Our study revealed that HFD induced the down-regulation of the IL-10 level and the used GAG treatment could sufficiently increase the expression of IL-10 to a greater extent than the control (ISG > IQG > GbG), such as the anti-obesity effect of HFD related reports." (PMID 28327528, 2017). "Also, additional studies including normal weight subjects with an OSA diagnosis are of great importance in order to accurately determine whether IL-10 may be useful as a marker of increased risk for OSA and insulin resistance, even in the absence of obesity." (PMID 25944984, 2015). "We then corroborated that most of the subjects showing low systemic levels of IL-10 and high AHI value also had increased insulin resistance, suggesting a direct association among OSA, anti-inflammatory factors, and metabolic abnormalities irrespective of obesity." (PMID 25944984, 2015). "We could not see any differences in the expression of IL-12 (M1) vs. IL-10 (M2) macrophages in the mammary tumor microenvironments of obese, overweight or lean mice, suggesting that obesity is not particularly related to M1 or M2 macrophages in the mammary tumor microenvironment." (PMID 25599228, 2015). "The presence of such regulatory macrophages in obese adipose tissue may be ideal given their secretion of the anti-inflammatory cytokines, IL-10 and TGFβ1, and the lack of antigen presentation to T helper cells that could exacerbate chronic inflammation in obesity." (PMID 24465472, 2014). "However, the effect of obesity on IL10 concentration in children is not clear." (PMID 23941335, 2013). "Sixth, This study only examined the relationship between IL-6, TNF-α, and IL-2 levels and psychiatric symptoms and obesity, without testing other factors, particularly C-reactive protein (CRP) and interleukin-10 (IL-10)." (PMID 40791199, 2025). "A single study found a decrease in IL-10 in people with BED, although this was also found in individuals with obesity who did not have BED27." (PMID 41034374, 2025). "The elevated IL-10 levels in the WAT of obese and T2DM women relative to men were primarily attributed to obesity rather than to circulating estrogen." (PMID 39575382, 2024). "The cytokine production capacity of children with obesity was higher for TNF, IL-1β, IL-6, IL-10, IL-1Ra, IL-12p70, MCP-1, RANTES, and MIP1α, but not IL-8, indicating an overall hyperresponsive state compared to controls." (PMID 38741712, 2024). "HF+FO/E, but not HF+FO/D, was able to prevent the changes triggered by obesity in TNF-α, Il-10, and resistin secretion in ING and RP depots." (PMID 33652751, 2021). "Moreover, the lack of higher levels of IL-10, a pivotal anti-inflammatory cytokine, points out the absence of a counter-regulatory process, which in turn may contribute to the chronic, low-grade inflammation typical of obesity." (PMID 33642987, 2021). "TAN, but not HMF, reduced adipocyte size in the mice with pre‐existent obesity, while HMF, but not TAN, decreased fat accumulation in the liver and also significantly increased the levels of an anti‐inflammatory cytokine, IL‐10." (PMID 33841818, 2021). "On the other hand, levels of Il10 were reduced in the absence of KLF3, in line with recent findings that IL-10 blockade protects against diet-induced obesity and elicits browning of AT51." (PMID 32523103, 2020). "Altogether, for the first time, IL-1α, IL-10, EGF, and IFN-γ were shown to differ between AN and HCs, and between AN and individuals with obesity with or without BED." (PMID 31450770, 2019).
Obesity (continued). "Consistent with our hypothesis, certain inflammatory markers, as IL-2, IL-10, IFN-γ and IL1-α, were found to differ between AN and HCs, as well as between AN and participants with obesity with or without BED." (PMID 31450770, 2019). "We also found that IL-10 levels were significantly influenced by EDs diagnosis (being essentially higher in AN and lower in BED), by BMI (being higher in normal-weight and lower in class II/III obesity but not influenced by depression." (PMID 31450770, 2019). "Therefore, further investigations are still needed to identify SNPs in IL-10 and other inflammatory/anti-inflammatory cytokines with the aim to determine whether such markers could be used for individually evaluating the risk to develop OSA, even at early stages and regardless of obesity." (PMID 25944984, 2015). "Serum IL-10 is significantly reduced in morbidly obese subjects with severe OSA while also showing a clear relationship with a state of hyperinsulinemia and insulin resistance probably regardless of obesity in the present sample." (PMID 25944984, 2015).